CANX (calnexin)
Diseases named in the same sentence as CANX in open-access papers (continued):
Sharing a sentence is not in itself a finding about the gene and the disease.
infection (continued). "In cells expressing UL148 (i148HA), we observed that calnexin, HRD1, EDEM1, and VCP colocalized with UL148 at prominent globular structures reminiscent of those observed during infection." (PMID 31822584, 2019). "Vaccine of calnexin in glucan particles elicited calnexin-specific CD4+ T cells and resistance to infection by B. dermatitidis, H. capsulatum, Pseudogymnoascus (Geomyces) destructans, Fonsecaea pedrosoi, and A. fumigatus." (PMID 28344577, 2017). "At 24 hours post-infection, TGON2 and CANX localized near to dsRNA, confirming that TGON2 is relocalizing to similar sites as CANX." (PMID 27682269, 2016). "Using TUFM (Tu translation elongation factor, mitochondrial) and calnexin as markers for mitochondria and ER, respectively, we observed that EV-A71 infection did not alter the overall distribution of cellular organelle at 4 hpi or 8 hpi." (PMID 40522993, 2025). "However, a marked protein overexpression of ER-stress markers such as calnexin, calreticulin and CHOP/GADD 153 have been observed in Vero cell and primary rat neurons 36 h post-infection with recombinant A75/17-V CDV." (PMID 32054075, 2020). "The administration of calnexin in glucan particles elicited calnexin-specific CD4+ T cells, and vaccinated mice demonstrated resistance to infection by Blastomyces dermatitidis, Histoplasma capsulatum, Pseudogymnoascus (Geomyces) destructans, Fonsecaea pedrosoi, and A. fumigatus." (PMID 32722452, 2020). "However, a limitation for the development of a calnexin-specific antifungal vaccine is the low precursor frequency of naive endogenous CD4+ T cells and the modest expansion and protective efficacy after vaccination and infection." (PMID 41061037, 2025). "Furthermore, increased levels of TAP-transporters (TAP1, TAP2), MHC I components B2M and HLAs, together with the ER chaperons calreticulin (CALR) and calnexin (CALN), and aminopeptidases ERAP1 and ERAP2 indicated upregulation of MHC I dependent antigen presentation with progressing infection." (PMID 37112941, 2023). "Importantly, VAPB knockdown did not alter pUL34, calnexin or GM-130 localization during infection, arguing against an indirect effect of VAPB on cellular vesicles and trafficking." (PMID 30717447, 2019). "Hence, the accumulation of HRD1 and calnexin at unusual structures during wild-type but not UL148-null infection may suggest that the structures form in response to defects in ER quality control (ERQC) caused by UL148." (PMID 31822584, 2019). "Remarkably, similar outcomes were observed following infection with PRRSV where the proteolytic cleavage of ATF6 does not occur, nor is there an increase in the expression of ATF6 target genes, such calnexin or calreticulin." (PMID 41157573, 2025). "Upon infection of the dually labeled D. discoideum strains with mCerulean-producing L. pneumophila JR32, GBP-GFP co-localized with calnexin-mCherry but not with P4C-mCherry." (PMID 40300029, 2025). "We performed immunofluorescence using the ER marker Calnexin and the Golgi marker GM130 and did not observe any differences in the ER and Golgi morphology upon infection with A. baumannii in A549 cells." (PMID 33436835, 2021). "In this study, only tapasin was upregulated in both treatment/infection groups while CALR, ERp57, and CANX were either downregulated or not differentially expressed." (PMID 31121853, 2019).
cancer (38 papers, 2010 to 2026). A tumor composed of atypical neoplastic, often pleomorphic cells that invade other tissues. "Survival analysis revealed that CANX was associated with a greater risk of most cancers, with the LGGGBM group exhibiting the most significant p-value." (PMID 39990231, 2025). "The upregulation of calnexin has been associated with a worse prognosis in several types of cancer, but results are still controversial." (PMID 34885011, 2021). "Calnexin gene-silencing significantly reduced cell survival and increased cancer cell susceptibility to 5FU chemotherapy." (PMID 27369741, 2016). "Most APP genes were down-regulated in cancers, excluding the cochaperones calreticulin and calnexin, which participate in cancer pathology." (PMID 41477871, 2026). "This study found that CANX was upregulated in PCa and acted as a target gene of miR-505-3p, and overexpression of CANX decreased the suppressive effects of circFAM126A and overexpression of miR-505-3p on cancer malignancy." (PMID 38230215, 2024). "Flow cytometry showed that the promoting effect of circFMA126A knockdown or miR-505-3p overexpression on cancer apoptosis rate was reversed by overexpression of CANX." (PMID 38230215, 2024). "Cell-surface PDIA3 has also been shown to act with glycosylated calnexin to reduce extracellular disulfide bonds and make ECM more susceptible to degradation by cancer cells." (PMID 35196163, 2022). "The difference in properties between the mesothelium and the epidermis is determined by the function of E and N calnexin, and these factor proteins can be used as targets for cancer therapy." (PMID 35251569, 2022). "As an integral chaperon protein of the ER, calnexin (CANX) promotes cancer cell growth and proliferation." (PMID 33194991, 2020). "As well as the calcium-binding proteins, calreticulin and calnexin, were also previously detected in other cancer cells." (PMID 26269723, 2014). "We further evaluated the potential role of CANX as an oncogene across various cancers." (PMID 39990231, 2025). "The lectin chaperones calreticulin (CALR) and calnexin (CANX), together with their co-chaperone PDIA3, are increasingly implicated in studies of human cancers in roles that extend beyond their primary function as quality control facilitators of protein folding within the endoplasmic reticulum (ER)." (PMID 35860021, 2022). "So far, CANX has not been described in PCa but its altered expression has been associated with other cancers." (PMID 35267445, 2022). "Therefore, immunofluorescence staining of the ER-membrane bound protein, calnexin, was conducted in control and treated cancer cells." (PMID 28915644, 2017). "A number of molecular chaperones are up-regulated in cancer in response to ER stress, including heat shock proteins (such as GPR78 and GPR94) and lectin-like chaperones (such as calnexin and calreticulin)." (PMID 30115016, 2018). "We further probed SPAG9 co-localization with various cell organelles by using multiple markers for Golgi body (GM130), endoplasmic reticulum (calnexin), nuclear envelope (lamin A/C) and mitochondria (MTCO2) in high grade invasive UM-UC-3 cancer cells." (PMID 24349057, 2013). "Immunocytochemistry of calnexin (CNX), Bap31 (an ER marker protein), and Tim23 (a mitochondrial marker protein) confirmed ER- and mitochondria-derived vacuolation in Eer1- or CB-5083-treated cancer cells." (PMID 38218922, 2024). "Microarray data suggested that 5 days of vitamin C supplementation under normal physiological condition, but not under cancer condition, induce an upregulation of calnexin isoform." (PMID 29971019, 2018).
cancer (continued). "Moreover, other genes from diverse functional groups appeared in our analysis, such as signal transducers promoting cancer growth (CD53, RAB33A, GNA11, CANX, OCRL, GIPC1, and SOS1), microtubule formation (KIF21B) and cell migration (ASAP2)." (PMID 29535628, 2018). "Interestingly,KIAA0101, CANX and NME1 haveall been found to be highly expressed in at least eight different carcinomas,including breast, lung and prostate, representing possible globaltumor markers." (PMID 21423607, 2011). "WB results validated the expression of EVs specific markers and cancer specific marker, we obtained distinct bands for CD9, TSG101 and PDL-1 verifying the presence of the EVs specific markers and cancer specific marker, respectively, while calnexin as an EVs’ negative marker." (PMID 35624582, 2022).
cardiovascular disease (1 paper, 2021). "Calnexin is an ER chaperone that has been implicated in cardiomyocyte viability and in ER stress, a prominent clinical feature of cardiovascular disease, while ITPR1 mediates the influx and release of intracellular Ca2+ and is regulated by the palmitoylation cascade of ZDHHC16/ZDHHC6." (PMID 34252155, 2021).
myopathy (1 paper, 2013). A disease of the muscle in which the muscle fibers do not function properly. "Four molecular chaperones, glucose-regulated protein 94 (GRP94), glucose-regulated protein 78 (GRP78), calreticulin and calnexin and valosin containing protein (VCP) were highly expressed in GNE myopathy." (PMID 23472144, 2013).
CANX also shares sentences with these, for which no sentence is quoted: amyotrophic lateral sclerosis (2 papers); fatty liver disease (2); multiple sclerosis (2); osteosarcoma (2); Parkinson disease (2); adenoma (1); AIDS (1); Arthritis (1); Azoospermia (1); brain cancer (1); Burkitt lymphoma (1); cholestasis (1); colorectal tumours (1); corticotroph adenoma (1); diabetic nephropathy (1); encephalitis (1); Ewing sarcoma (1); gastric ulcer (1); gastritis (1); gonadotroph adenoma (1); heart disease (1); Hepatic steatosis (1); hereditary spastic paraplegia (1); HIV-1 infection (1); hyperglycaemia (1); Hyperoxaluria (1); infertile (1); lung diseases (1); MALT lymphoma (1); medulloblastoma (1).
A further 19 diseases each share a sentence with CANX in 1 paper.